LILRA6 (leukocyte immunoglobulin like receptor A6)
Description:
May act as receptor for class I MHC antigens.
Synonyms: ILT-8; ILT8; CD85b; ILT5; LILRB6
Tractability: Antibody: UniProt predicts a signal peptide or a membrane-spanning region; its Gene Ontology location is reachable by antibodies, with medium confidence; the Human Protein Atlas places it where antibodies can reach. PROTAC: its protein half-life has been measured.
Gene: Protein-coding gene on chromosome 19 (54,236,590 to 54,242,790, reverse strand). Ensembl gene ENSG00000244482.
Subcellular location: Membrane
Subcellular location (Human Protein Atlas): Plasma membrane; Cytosol
Pathways (Reactome):
Immune System: Immunoregulatory interactions between a Lymphoid and a non-Lymphoid cell
Gene Ontology:
Molecular function: inhibitory MHC class I receptor activity
Biological process: cytokine-mediated signaling pathway; immune response-inhibiting cell surface receptor signaling pathway; cell surface receptor signaling pathway
Cellular component: plasma membrane; membrane
Genetic constraint (gnomAD): Loss-of-function variants: 16 observed, 38.08 expected, observed/expected ratio (o/e) 0.42, 90% interval 0.28 to 0.64. The synonymous counts are far from expectation, so gnomAD's model fits this gene poorly and the ratio says little. Missense variants: 300 observed, 424.41 expected, observed/expected ratio (o/e) 0.71, 90% interval 0.64 to 0.78. Synonymous variants: 130 observed, 168.31 expected, observed/expected ratio (o/e) 0.77, 90% interval 0.67 to 0.89.
Homologues: Orthologues: chimpanzee LILRB3 (81% identical), macaque LILRB3 (75% identical), macaque LILRA6 (72% identical), mouse Pira12 (54% identical), rat Pirb (54% identical), mouse Pira2 (53% identical), mouse Pira13 (53% identical), mouse Pira1 (52% identical), mouse Lilra6 (52% identical), mouse Pirb (52% identical), rat LOC134485274 (52% identical), rat Lilrb3 (45% identical), and 4 more. Paralogues in human: LILRB3 (89% identical), LILRA4 (68% identical), LILRB5 (66% identical), LILRA1 (65% identical), LILRB1 (65% identical), LILRA2 (65% identical), LILRB2 (65% identical), LILRA5 (39% identical), LILRB4 (36% identical), KIR3DL1 (28% identical), KIR3DL2 (28% identical), KIR3DL3 (27% identical), and 13 more.
Diseases named in the same sentence as LILRA6 in open-access papers:
LILRA6 is named in the same sentence as 15 diseases in open-access papers, as found by Europe PMC text mining. Sharing a sentence is not in itself a finding about the gene and the disease. The quoted sentences say what the papers report.
multiple sclerosis (2 papers, 2025). A progressive autoimmune disorder affecting the central nervous system resulting in demyelination. "Additionally, LILRA6 has been implicated in rheumatoid arthritis and multiple sclerosis, while MCM10 has been identified in the context of immunodeficiency disease, with or without congenital cardiomyopathy." (PMID 40386946, 2025). "Upregulated expression of LILRA6 has been observed in patients with Multiple Sclerosis, severe aplastic anemia, rheumatoid arthritis, and non-small cell lung cancer following neoadjuvant chemo-immunotherapy." (PMID 40577278, 2025).
lung diseases (1 paper, 2024). "A recent study demonstrated that nine genes (CD274, CEACAM1, CR1, FCGR1A/B, IFITM1, IRAK3, LILRA6, MAPK14, and PDCD1LG2) showed 100% sensitivity and specificity that distinguished patients with active TB from those with other lung diseases (OPD)." (PMID 38674369, 2024).
osteosarcoma (1 paper, 2022). A usually aggressive malignant bone-forming mesenchymal neoplasm, predominantly affecting adolescents and young adults. "Finally, a 5-gene prognostic model consisting of COL13A1, TNFRSF1A, LILRA6, CTNNBIP1, and CD180 was established for predicting the prognosis of osteosarcoma." (PMID 36035315, 2022).
cancer (4 papers, 2021 to 2025). A tumor composed of atypical neoplastic, often pleomorphic cells that invade other tissues. "LILRA6 has not been reported to be significantly associated with cancer development, serving as a new potential biomarker for predicting OS prognosis." (PMID 36035315, 2022). "Despite these mechanistic insights, our study is the first to implicate LILRA6, CACNG6, and PRSS33 in cancer-related symptoms." (PMID 40577278, 2025). "Besides, pan-cancers analysis showed that LILRA6 was not specific to PCPG." (PMID 33795528, 2021).
tumor (2 papers, 2016 to 2021). "In summary, by using a comprehensive bioinformatics analysis, we identified three tumor microenvironment-related genes (ADGRE1, CCL18, and LILRA6) which were closely associated with the prognosis of PCPG." (PMID 33795528, 2021). "The results showed that only LILRA6 were differently expressed between tumor and normal tissues." (PMID 33795528, 2021). "Finally, three tumor microenvironment-related genes (ADGRE1, CCL18, and LILRA6) significantly associated with PCPG prognosis were obtained by survival analysis." (PMID 33795528, 2021). "Since LILRB3 and LILRA6 genes are highly polymorphic the interaction may influence an individual's immune response to tumours." (PMID 26769854, 2016). "The balance of signals transmitted by inhibitory LILRB3 and activating LILRA6 might therefore determine whether an immune response is initiated to the dead tumour cell, thereby to influence the wider immune response within the tumour microenvironment." (PMID 26769854, 2016). "Therefore, the development of specific LILRA6 inhibitors may provide an attractive target for anti-tumor immunotherapy in further study." (PMID 33795528, 2021). "The promoter methylation level of LILRA6 was also significantly lower tumor tissue compared with normal tissue." (PMID 33795528, 2021).
LILRA6 also shares sentences with these, for which no sentence is quoted: rheumatoid arthritis (2 papers); aplastic anemia (1); atopic dermatitis (1); congenital cardiomyopathy (1); dyskeratosis congenita (1); immunodeficiency disease (1); Miscarriage (1); myeloid neoplasm (1); non-small cell lung carcinoma (1); sarcoidosis (1).